CACNA2D3 (calcium voltage-gated channel auxiliary subunit alpha2delta 3)
Description:
The alpha-2/delta subunit of voltage-dependent calcium channels regulates calcium current density and activation/inactivation kinetics of the calcium channel. Acts as a regulatory subunit for P/Q-type calcium channel (CACNA1A), N-type (CACNA1B), L-type (CACNA1C OR CACNA1D) but not T-type (CACNA1G) (By similarity).
Synonyms: HSA272268; alpha2delta-3
Tractability: Small molecule: an approved drug acts on it; a high-quality ligand is known; it belongs to a druggable protein family. Antibody: UniProt predicts a signal peptide or a membrane-spanning region. PROTAC: ubiquitination databases record sites on it; its protein half-life has been measured.
Gene: Protein-coding gene on chromosome 3 (54,122,427 to 55,074,557, forward strand). Ensembl gene ENSG00000157445.
Subcellular location: Membrane
Subcellular location (Human Protein Atlas): Nucleoplasm; Principal piece
Pathways (Reactome):
Neuronal System: Presynaptic depolarization and calcium channel opening
Gene Ontology:
Molecular function: voltage-gated calcium channel activity
Biological process: calcium ion transmembrane transport; calcium ion transport; cellular response to insulin-like growth factor stimulus; regulation of presynapse organization
Cellular component: voltage-gated calcium channel complex; GABA-ergic synapse; membrane; presynaptic active zone membrane
Genetic constraint (gnomAD): Loss-of-function variants: 33 observed, 97.29 expected, observed/expected ratio (o/e) 0.34, 90% interval 0.26 to 0.45. The upper end of that interval is the gene's LOEUF score, 0.45, which puts it in group 2 of 6, group 1 being the genes least tolerant of losing a copy. Missense variants: 872 observed, 1,006.9 expected, observed/expected ratio (o/e) 0.87, 90% interval 0.82 to 0.92. Synonymous variants: 424 observed, 378.2 expected, observed/expected ratio (o/e) 1.12, 90% interval 1.03 to 1.22.
Homologues: Orthologues: chimpanzee CACNA2D3 (100% identical), macaque CACNA2D3 (99% identical), pig CACNA2D3 (98% identical), mouse Cacna2d3 (98% identical), dog CACNA2D3 (98% identical), rat Cacna2d3 (94% identical), rabbit CACNA2D3 (91% identical), guinea pig CACNA2D3 (89% identical), tropical clawed frog cacna2d3 (87% identical), zebrafish cacna2d3 (76% identical), zebrafish CACNA2D3 (71% identical), Drosophila melanogaster stj (36% identical), and 1 more. Paralogues in human: CACNA2D4 (59% identical), CACNA2D2 (30% identical), CACNA2D1 (29% identical), CACHD1 (22% identical).
Diseases named in the same sentence as CACNA2D3 in open-access papers:
CACNA2D3 is named in the same sentence as 58 diseases in open-access papers, as found by Europe PMC text mining. Sharing a sentence is not in itself a finding about the gene and the disease. The quoted sentences say what the papers report.
gastric cancer (14 papers, 2009 to 2023). A primary or metastatic malignant neoplasm involving the stomach. "High CACNA2D3-expression was associated with improved survival outcomes in advanced gastric cancer: patients with detectable CACNA2D3 gene methylation had a significantly shorter survival time than patients without this methylation." (PMID 36046118, 2021). "The promoter of CACNA2D3 was shown to be highly methylated in gastric cancer, and this was associated with a low survival rate." (PMID 31001468, 2019). "Another study found that promoter methylation of CACNA2D3 was frequently detected in gastric cancer, which was associated with poor prognosis of the disease." (PMID 23560067, 2013). "In support of a direct role for α2δ-2 in prostate cancer development, gabapentin, an inhibitor of α2δ subunits, was capable of inhibiting tumor development in xenografts.** In contrast, the CACNA2D3 gene, which encodes for α2δ-3, has been identified as a methylation site in gastric cancer." (PMID 36520928, 2022). "Similarly, the related CACNA2D3 locus, encoding the CaV-α2δ3 subunit, has been identified as a frequent site of methylation in gastric cancer." (PMID 26010603, 2015). "The level of physical activity is also important in gastric cancer, where a higher level of methylation of suppressor gene the Calcium Voltage-Gated Channel Auxiliary Subunit Alpha2delta 3 (CACNA2D3) has been noticed in less physically active people." (PMID 34884790, 2021). "In a study among gastric cancer patients, methylation of CACNA2D3, a known tumor-suppressor gene, was higher among those who did not exercise than among those who exercised more than an hour per week." (PMID 30768632, 2019). "The CACNA2D3 gene has been suggested as a putative tumor suppressor gene in lung cancer, renal cell cancer neuroblastoma and squamous cell esophageal cancer, and has been identified as an indicator of prognosis in gastric cancer." (PMID 25351872, 2015). "In addition, an elevated intracellular Ca2+ level was detected when CACNA2D3 was introduced into cells, which was similar to the results of CACNA2D3 in gastric cancer cells and CACNA2D2 in non-small cell lung cancer cells." (PMID 23560067, 2013). "Although CACNA2D3 has been associated with the poor outcome of gastric cancer, the effect of CACNA2D3 on ESCC development is not clear." (PMID 23560067, 2013). "Also, CACNA2D3 has been suggested to be a tumour suppressor gene in esophageal squamous cell carcinoma and has recently been found to be a poor prognostic factor in gastric cancer." (PMID 19686582, 2009). "RASSF1A, p14ARF, and MGMT; CHRNA3, DOK1, and GNMT; p16, hMLH1, MINT1, MINT2, MINT12, MINT25, and MINT31; APC, CDH1, MHL1, CDKN2A, CDKN2B, and RUNX3; CDH1; DKK3; PTEN; MGMT; TFPI2; CACNA2D3; PCDH10; SOX2; MAL; and COX2 were previously reported to be hypermethylated in gastric cancer." (PMID 26121593, 2015). "Furthermore, methylation of CACNA2D3, but not CACNA2D2 was associated with significantly shorter survival, making it a useful prognostic marker for patients with gastric cancer." (PMID 26010603, 2015).
autism (9 papers, 2015 to 2024). Persistent deficits in social interaction and communication and interaction as well as a markedly restricted repertoire of activity and interest as well as repetitive patterns of behavior. "Mice lacking α2δ-3 show increased anxiety-like behavior and defective object-based memory, indicating a strong association between the CACNA2D3 gene and autism." (PMID 39770450, 2024). "Our data provide support for the reported association of CACNA2D1 and CACNA2D3 genetic aberrations with autism and the high comorbidity of epilepsy in individuals with autism." (PMID 32414783, 2020). "Furthermore, analyses of gene-disrupting mutations in individuals with autism highlighted CACNA2D3 among autism susceptibility genes." (PMID 32414783, 2020). "The human homolog of UNC-36, CACNA2D3 has also been associated with autism." (PMID 31805042, 2019). "Interestingly, in a previous study of 343 families, each with a single child on the autism spectrum, and at least one unaffected sibling, a single de novo splice site mutation was found in CACNA2D3, one of many gene-disrupting mutations identified." (PMID 26386135, 2015). "Several potential autism-causing mutations in the coding sequence of CACNA2D1 and CACNA2D3 have been identified in patients with ASD." (PMID 39770450, 2024). "Furthermore, both CACNA2D1 and CACNA2D3 genes are included in the Simons Foundation Autism Research Initiative (SFARI) gene list, which serves as an extensive database that includes all genes associated with autism risk." (PMID 39770450, 2024). "Furthermore, a recent study links conditional CACNA2D3 knockout in parvalbumin-expressing cortical interneurons to autism-like behavior." (PMID 39770450, 2024). "Cacna2d3, Chd8, and Tbr1 are associated with autism and ID generally but not with any named syndromes." (PMID 39431203, 2024). "A copy number variation study in autism also revealed a deletion in CACNA2D3." (PMID 26386135, 2015). "Taken together, our data demonstrate a critical role for cacna2d3 in sensory filtering, a process that is disrupted in human CNS disorders, e.g. ADHD, schizophrenia, and autism." (PMID 35834485, 2022). "CACNA2D3 protein plays an essential role in sensory filtering and habituation, a process of ignoring unimportant stimuli, impaired in many neuropsychiatric disorders (ADHD, schizophrenia, and autism)." (PMID 38891944, 2024).
autism spectrum disorder (6 papers, 2021 to 2025). A spectrum of developmental disorders that includes autism, and Asperger syndrome. "Several rare missense variants in CACNA2D1 (coding for α2δ-1) and CACNA2D3 (coding for α2δ-3) genes were identified in patients with autism spectrum disorder (ASD)." (PMID 39770450, 2024). "Loss of function mutations of Cacna2d3 have been recently identified as risk mutations for autism spectrum disorders (ASDs) in humans." (PMID 35410870, 2022). "CACNA2D3 has been found to possess a potential tumor suppressor function in multiple carcinomas [S35] and loss‐of‐function mutations have been identified as risk factors for autism spectrum disorders (ASDs) in humans [S36–S39]." (PMID 40468979, 2025). "Disrupting splice site mutation in CACNA2D3 has been found in autism spectrum disorder." (PMID 38891944, 2024). "This is insofar surprising as neurological disorders have been linked to aberrant α2δ subunit expression in humans: mutations in CACNA2D1 and CACNA2D2 with epilepsy, CACNA2D3 is a potential risk gene for autism spectrum disorders, and all three genes with schizophrenia." (PMID 33679366, 2021). "Here, we studied response properties of neurons in the inferior colliculus (IC) in mice lacking Cacna2d3, a risk gene for autism spectrum disorders (ASDs)." (PMID 35410870, 2022).
breast carcinoma (6 papers, 2018 to 2023). "Likewise, the methylation-dependent silencing of CACNA2D3 has been proposed as a biomarker for the risk of metastasis in breast cancer." (PMID 36520928, 2022). "Most of these genes were associated with cancers of metabolic systems (DUSP6, SGK1, BMP4, RASGRF1, GDF15) followed by breast cancer (CACNA2D3, ITGB7), cancers of the central nervous system (PRKCA), or leukemia (MECOM, JAK3)." (PMID 36624125, 2023). "Methylation-dependent transcriptional silencing of CACNA2D3 was shown to contribute to the metastatic phenotype of estrogen-receptor-positive primary breast cancer, again illustrating a protective nature of the gene." (PMID 36046118, 2021). "Similarly, suppression of CACNA2D3 by methylation was found to promote the metastatic phenotype of breast cancer." (PMID 31001468, 2019).
endometrial cancer (6 papers, 2020 to 2024). Primary or metastatic malignant neoplasm involving the endometrium (mucous membrane that lines the endometrial cavity). "Studies have shown that CACNA2D3/CA2 + induces phosphorylation of p38 MAPK in endometrial cancer, which in turn induces apoptosis in tumor cells." (PMID 36624463, 2023). "A recent work evaluated the role of CACNA2D3 (calcium voltage-gated channel auxiliary subunit α2δ3) in endometrial cancer." (PMID 36230654, 2022). "Endometrial cells treated with P4 increased the expression of CACNA2D3 and the intracellular Ca+2 levels, preventing endometrial cancer cell proliferation and inducing apoptosis." (PMID 36230654, 2022). "CACNA2D3 calcium channel expression showed the opposite effect to the other channels in endometrial cancer." (PMID 36230654, 2022). "CACNA2D3 is expressed in low levels in endometrial cancer tissues and cells." (PMID 35045818, 2022). "CACNA2D3 was downregulated in esophageal squamous cell carcinoma, nasopharyngeal carcinomas and gliomas and has an antitumor role in endometrial cancer." (PMID 33240314, 2020).
esophageal squamous cell carcinoma (6 papers, 2009 to 2022). Esophageal squamous cell carcinoma (ESCC) is a type of esophageal carcinoma (EC) that can affect any part of the esophagus, but is usually located in the upper or middle third. "CACNA2D3, as a new tumor suppressor gene, can significantly inhibit lymph node metastasis of esophageal squamous cell carcinoma in clinical studies." (PMID 35045818, 2022).
epilepsy (5 papers, 2020 to 2023). A brain disorder characterized by episodes of abnormally increased neuronal discharge resulting in transient episodes of sensory or motor neurological dysfunction, or psychic dysfunction. "Focusing on moderate-impact “high-quality variants”, we also identified mutations in GASH/Sal genes that were previously reported as polymorphisms associated with epilepsy, such as Cacna1a, Cacna2d3, Grik1 and Jup." (PMID 32168507, 2020). "Furthermore, Cacna2d3, a gene encoding voltage-dependent calcium channel subunit α2/δ3, has been implicated as a candidate gene for epilepsy." (PMID 37545878, 2023). "The Cacna1a and Cacna2d3 genes, which encode calcium voltage-gated channel subunit alpha1A and calcium voltage-gated channel auxiliary subunit alpha2delta3, respectively, are involved in different types of epilepsy, as described in the literature." (PMID 32168507, 2020). "There is no literature specifically supporting the role of CACNA2D3 in causing seizures or epilepsy, but it encodes for a member of the α2δ subunit family of voltage-gated calcium channels, which have a role in epilepsy and antiepileptic drug pharmacology." (PMID 33441621, 2021). "Finally, we use our analysis to prioritize new candidate genes for epilepsy (i.e. ANK2, CACNA1E, CACNA2D3, GRIA2, DLG4) for further validation." (PMID 33441621, 2021).
glioma (4 papers, 2019 to 2025). A benign or malignant brain and spinal cord tumor that arises from glial cells (astrocytes, oligodendrocytes, ependymal cells). "CACNA2D3 is downregulated in gliomas and functions as a tumor suppressor." (PMID 40777122, 2025). "CACNA2D3 suppressed cell proliferation, migration and invasion in glioma." (PMID 40777122, 2025).
neuroblastoma (4 papers, 2006 to 2021). Neuroblastoma (NB) is the most common solid, extracranial childhood tumor. "CACNA2D3 is highly expressed in neuroblasts and neuroblastomas with a favorable prognosis, while its expression is downregulated in those with a poor prognosis." (PMID 25351872, 2015). "These include STAT3, IGSF4 and CACNA2D3, and they should also be studied in further detail to determine their possible role in neuroblastoma pathogenesis." (PMID 16989664, 2006). "In neuroblastomas with poor prognosis, the expression of CACNA2D3 is often downregulated." (PMID 31001468, 2019). "Among others, these include CASP9 and CDC42 (1p36), which have already been studied in neuroblastoma; CACNA2D3 (3p21-p22), which was recently proposed as a tumor suppressor gene in lung cancer; IGSF4 (11q23), which is a known tumor suppressor gene in several cancers; and DLK1 (14q)." (PMID 16989664, 2006). "The prognostic effects of age related genes ALCAM, CACNA2D3, DST, EPB41L4A and KIF1B in pediatric neuroblastoma patients were determined by Kaplan-Meier survival." (PMID 34116676, 2021). "Neuroblastoma patients with higher expression levels of ALCAM, CACNA2D3, DST, EPB41L4A or KIF1B had better clinical overall survival in TARGET dataset, GSE49710 dataset and GSE85047 dataset." (PMID 34116676, 2021). "We found that ALCAM, CACNA2D3, DST, EPB41L4A and KIF1B were associated with the favorable prognosis of MYCN non-amplified neuroblastoma patients." (PMID 34116676, 2021). "Next, we tried to determine the associations of ALCAM, CACNA2D3, DST, EPB41L4A and KIF1B in MYCN non-amplified neuroblastoma patients." (PMID 34116676, 2021). "And the higher expression levels of ALCAM, CACNA2D3, DST, EPB41L4A or KIF1B were associated with better prognosis of MYCN non-amplified neuroblastoma patients." (PMID 34116676, 2021). "Interestingly, high expression levels of ALCAM, CACNA2D3, DST, EPB41L4A or KIF1B were not only associated with the prognosis of MYCN non-amplified neuroblastoma patients, but also were associated with the prognosis of all neuroblastoma patients." (PMID 34116676, 2021). "MYCN non-amplified neuroblastoma patients with lower expression levels of ALCAM, CACNA2D3, DST, EPB41L4A or KIF1B were with lower overall survival in TARGET dataset, GSE49710 dataset and GSE85047 dataset." (PMID 34116676, 2021). "ALCAM, CACNA2D3, DST, EPB41L4A and KIF1B were highly expressed in MYCN non-amplified younger neuroblastoma patients." (PMID 34116676, 2021). "Moreover, the prognostic significances of ALCAM, CACNA2D3, EPB41L4A and KIF1B in MYCN non-amplified pediatric neuroblastoma were not previously reported." (PMID 34116676, 2021). "MYCN non-amplified neuroblastoma is a heterogeneous disease and could be divided into sub-groups based on age or the expression levels of ALCAM, CACNA2D3, DST, EPB41L4A and KIF1B." (PMID 34116676, 2021). "Furthermore, using multivariate cox regression, we determined the correlations of age, ALCAM, CACNA2D3, DST, EPB41L4A or KIF1B expression in the prediction of the clinical overall survival of MYCN non-amplified neuroblastoma patients." (PMID 34116676, 2021).
Alzheimer disease (3 papers, 2016 to 2024). A progressive, neurodegenerative disease characterized by loss of function and death of nerve cells in several areas of the brain leading to loss of cognitive function such as memory and language. "Studies have shown that CACNA2D3 is associated with cognitive ability and intelligence and is a predisposing risk factor for Alzheimer’s disease." (PMID 33525573, 2021). "The presence of the CACNA2D3 (0.938, 0.902 − 0.975, P = .001), INPP5D (0.844, 0.802 − 0.888, P < .001), RBM47 (0.937, 0.891 − 0.985, P = .011) and TBXAS1 (0.965, 0.934 − 0.998, P = .036) may be associated with a lower risk of Alzheimer’s disease." (PMID 39560568, 2024).
schizophrenia (3 papers, 2016 to 2024). A major psychotic disorder characterized by abnormalities in the perception or expression of reality. "Several studies of the CACNA2D3 gene reported associations with symptoms of schizophrenia." (PMID 27028512, 2016). "Amongst the lowest p-values were 2 genes that might be of theoretical interest: CACNA2D3, directly involved in regulating the intracerebral calcium homeostasis, and TNFSF10, a gene that is involved in apoptosis in schizophrenia." (PMID 27028512, 2016).
Anxiety (2 papers, 2019 to 2020). Intense feelings of nervousness, tension, or panic often arise in response to interpersonal stresses. "In particular, more than a half (four of seven: Cacna2d3, Mapk1, Pomc, and Syn1) of underexpression cases found here associate domestication with anxiety, which is the key trait for mutual trust within a human–pet pair, as demonstrated for dogs, sheep, and guinea pigs." (PMID 31921305, 2019). "Also, CACNA2D3 was under-expressed in the amygdala of rats exposed prenatally to valproic acid and coincided with social behavior abnormalities including heightened anxiety." (PMID 32848554, 2020).
asthma (2 papers, 2021 to 2025). "Most recently, a GWAS conducted in a Korean pediatric population identified CACNA2D3 (3p14.3) as a novel locus, with the lead variant showing an association with reduced risk of asthma and atopic dermatitis multimorbidity." (PMID 41516222, 2025). "The variant rs67026078, located within the intergenic region between CACNA2D3 and WNT5A, was associated with asthma exacerbations in children." (PMID 33923891, 2021).
dilated cardiomyopathy (2 papers, 2019 to 2025). Cardiomyopathy which is characterized by dilation and contractile dysfunction of the left and right ventricles. "In the close examination, 3 genes (Itgb6, Cacna2d3, and Cacna1c) were downregulated in 2-week-old cKO hearts, compared to 15 genes downregulated in KEGG_dilated cardiomyopathy pathway in 6-week-old cKO." (PMID 31787756, 2019).